TAF11L13 (TATA-box binding protein associated factor 11 like 13)
Gene: Protein-coding gene on chromosome 5 (17,632,088 to 17,632,684, forward strand). Ensembl gene ENSG00000283776.
Gene Ontology:
Molecular function: RNA polymerase II general transcription initiation factor activity; protein heterodimerization activity
Biological process: RNA polymerase II preinitiation complex assembly; transcription initiation at RNA polymerase II promoter
Cellular component: transcription factor TFIID complex; nucleus
Homologues: Orthologues: tropical clawed frog taf11 (45% identical), zebrafish taf11 (45% identical), Drosophila melanogaster Taf11 (42% identical), Caenorhabditis elegans taf-11.1 (34% identical), Caenorhabditis elegans taf-11.2 (28% identical). Paralogues in human: TAF11L10 (95% identical), TAF11L5 (95% identical), TAF11L6 (95% identical), TAF11L7 (95% identical), TAF11L8 (95% identical), TAF11L3 (94% identical), TAF11L4 (94% identical), TAF11L9 (94% identical), TAF11L2 (93% identical), LINC02218 (89% identical), TAF11L12 (88% identical), TAF11L11 (86% identical), and 2 more.